CXCL17 (C-X-C motif chemokine ligand 17)
Diseases named in the same sentence as CXCL17 in open-access papers (continued):
Sharing a sentence is not in itself a finding about the gene and the disease.
gastric cancer (7 papers, 2017 to 2025). A primary or metastatic malignant neoplasm involving the stomach. "We identified several consensus differentially expressed genes and these genes were further confirmed with literature mining; at last, two genes, that is, immunoglobulin J chain and C-X-C motif chemokine ligand 17, were screened as novel gastric cancer associated genes." (PMID 28232943, 2017). "According to the relevant study, CXCL17 not only plays an important role in the development and prognosis of gastric cancer, but is also related with some bacteria in the stomach." (PMID 37889664, 2023).
hepatocellular carcinoma (7 papers, 2014 to 2024). A malignant tumor that arises from hepatocytes. "In the present study, we characterized the prognostic value of CXCL17 in patients with hepatocellular carcinoma (HCC) and evaluated the association of CXCL17 with immune infiltration." (PMID 25303284, 2014). "In a recent study, the MTT assay revealed that high levels of CXCL17 helped the hepatocellular carcinoma cell lines HepG2 and Hepa1-6 survive." (PMID 38384293, 2024). "For example, exosomes from hepatocellular carcinoma cells delivering DLX6-AS1 into macrophages trigger microRNA-15a-5p/C-X-C motif chemokine ligand 17 (CXCL17) axis resulting in M2 macrophage polarization." (PMID 36153596, 2022). "Although ectopic CXCL17 expression promotes hepatoma HepG2 cell proliferation, the nature and role of CXCL17 in human HCC has not been elucidated." (PMID 25303284, 2014). "In another study, it was observed that CXCL17 could be used as a new prognosis marker to predict poor OS and RFS in hepatocellular carcinoma patients." (PMID 33489879, 2020).
pancreatic cancer (6 papers, 2012 to 2025). "CXCL17 induces immature myeloid dendritic cells to infiltrate human pancreatic cancer, thereby promoting the immune response." (PMID 34512623, 2021). "The CXC ligand family (CXCL5, CXCL9, CXCL10, CXCL11, and CXCL17) plays a vital role in regulating pancreatic cancer progression." (PMID 33393862, 2021). "In order to determine whether human cancer cells express CXCL17, an RT-PCR assay was performed using 54 human cancer cell lines (colorectal, gastric, renal, breast, non-small cell lung, pancreatic carcinoma, and melanoma)." (PMID 22952881, 2012). "Secretion of CXCL17 and ICAM2 was significantly decreased when IPMA progressed to pancreatic cancer, contributing to immune tolerance." (PMID 40427186, 2025). "Before pancreatic cancer development, particularly at the (IPMN) (intraductal papillary mucinous neoplasm) stage, increased secretion of CXCL17 and ICAM2 (intercellular adhesion molecule 2) led to the infiltration of cDCs, followed by T-cell-mediated cytolysis of tumor cells." (PMID 40427186, 2025). "Additionally, our study showed that CXCL17 was also expressed in some gastric and pancreatic carcinoma cell lines, but not in melanoma cell lines." (PMID 22952881, 2012).
lung adenocarcinoma (5 papers, 2020 to 2026). A carcinoma that arises from the lung and is characterized by the presence of malignant glandular epithelial cells. "Understanding this molecular pathway will facilitate the search for new active compounds that could interact with CXCL17 of some of the proteins that directly or indirectly affects the metastatic properties of lung adenocarcinomas." (PMID 38384293, 2024). "According to a recent study, CXCL17 may be involved in how lung adenocarcinoma (LUAD) spreads to the spine." (PMID 38384293, 2024).
colorectal cancer (4 papers, 2012 to 2025). A primary or metastatic malignant neoplasm that affects the colon or rectum. "A recent study performed in colorectal cancer (CRC) cells used highly expressed GPR35 and CXCL17 in drug-resistant tumor cells." (PMID 38384293, 2024).
influenza (4 papers, 2021 to 2025). An acute viral infection of the respiratory tract, occurring in isolated cases, in epidemics, or in pandemics; it is caused by serologically different strains of viruses (influenzaviruses) designated A, B, and C, has a 3-day incubation period, and usually lasts for 3 to 10 days. "In conclusion, our study provides preliminary evidence supporting a diagnostic potential of CXCL17 to distinguish severe pandemic influenza A(H1N1) from COVID-19 and other respiratory infections like PTB." (PMID 33717172, 2021). "CXCL17 not only differentiated pandemic influenza A(H1N1) from other respiratory infections but showed prognostic value for influenza-associated mortality and renal failure in machine-learning algorithms and regression analyses." (PMID 33717172, 2021). "Indeed, CXCL17 again was among the variables with the higher importance for influenza-associated mortality in a random forest analysis, showing an AUC of 0.70 to differentiate both groups in the ROC curve analysis." (PMID 33717172, 2021). "Indeed, in a bivariate logistic regression analysis using the variables identified in the random forest algorithm, only CXCL17, along with procalcitonin, showed significant association with influenza." (PMID 33717172, 2021). "In addition, we show that this chemokine may be useful as a prognostic biomarker in influenza patients, as serum levels of CXCL17 are associated with higher risk of renal failure and mortality." (PMID 33717172, 2021). "Collectively, these findings demonstrate that CXCL17 can be detected in the lungs during influenza and SARS-CoV-2 infection." (PMID 33717172, 2021). "We also noted that CXCL17 was increased among influenza patients that developed acute kidney injury (AKIN), and its levels were even higher in individuals requiring renal replacement therapy." (PMID 33717172, 2021). "Conversely, accumulated survival at days 28 and 60 following hospital admission was lower in influenza patients with serum levels of CXCL17 ≥1,128 pg/ml." (PMID 33717172, 2021). "The higher levels of CXCL17 in sera from influenza patients prompted us to investigate the possible cellular sources of CXCL17 during influenza." (PMID 33717172, 2021). "Overall, these preliminary data justify future efforts to address a possible role for CXCL17 during influenza." (PMID 33717172, 2021). "Overall, the dynamics of CXCL17 levels post-hospital admission were similar in survivors and deceased influenza patients." (PMID 33717172, 2021). "Accordingly, our data indicate that influenza patients with higher CXCL17 levels have lower survival, suggesting a possible pathogenic role for this chemokine." (PMID 33717172, 2021). "However, the maximum levels of CXCL17 were observed among influenza patients seeking medical attention three weeks after the onset of symptoms." (PMID 33717172, 2021). "Interestingly, we found that levels of CXCL17 increased early in influenza patients within the first two days following the onset of symptoms, and levels remained increased during the first two weeks of illness." (PMID 33717172, 2021). "Importantly, serum levels of CXCL17 at D0 were significatively higher in patients who died of influenza as compared to survivors." (PMID 33717172, 2021). "Next, we evaluated the dynamics of serum CXCL17 levels during influenza." (PMID 33717172, 2021). "To investigate whether CXCL17 may participate in immunity against the influenza A(H1N1) virus, we analyzed the tissue expression pattern of CXCL17 in lung autopsy specimens obtained from patients who died of influenza." (PMID 33717172, 2021). "Interestingly, while both human cell types produced high amounts of CXCL17 at 24 h, 48h, and 72h after the infection, A549 epithelial cells produced lower levels of CXCL17 in response to influenza as compared to macrophages." (PMID 33717172, 2021). "Cumulative survival rates in patients with influenza according with their serum CXCL17 levels." (PMID 33717172, 2021).
influenza (continued). "Thus, we addressed whether the CXCL17 expression found in the lungs of influenza- and SARS-CoV-2-infected patients could be also detected in the serum." (PMID 33717172, 2021). "However, further analyses are required to confirm a role for CXCL17 in influenza." (PMID 33717172, 2021). "Finally, we found some possible cellular sources of CXCL17 during influenza." (PMID 33717172, 2021). "Conversely, here we found that lungs infected with influenza and SARS-CoV-2 express CXCL17 in the whole cytoplasm of pneumocytes, as well as in infiltrating macrophages." (PMID 33717172, 2021). "Blood vessels and pleura did not express CXCL17 in lung autopsy specimens from influenza patients (data not shown)." (PMID 33717172, 2021). "Our findings may be also explained by possible different abilities of influenza and SARS-CoV-2 virus strains to induce local CXCL17 production and translocation to the blood according to their virulence." (PMID 33717172, 2021). "A caveat of our study is that CXCL17 levels were assessed only in influenza patients with severe pandemic influenza A(H1N1), but not in individuals with milder forms of the disease nor in persons with seasonal influenza infections." (PMID 33717172, 2021).
asthma (3 papers, 2022 to 2025). "Interestingly, we noticed a strong increase in CXCL17 expression in asthma, only at the lung epithelium." (PMID 40399607, 2025).
cervical cancer (3 papers, 2021 to 2026). A primary or metastatic malignant neoplasm involving the cervix. "The aim of this study was to study the clinical significance of CXCL17 in cervical cancer patients and its associations with epithelial-to-mesenchymal transition (EMT) markers." (PMID 41496085, 2026). "To clarify the clinical significance of CXCL17 expression in cervical cancer tissues, we study the association between CXCL17 expression and clinical parameters." (PMID 41496085, 2026). "Further investigation of the molecular mechanisms underlying the role of CXCL17 in the process of EMT in cervical cancer is needed." (PMID 41496085, 2026). "Another study performed with HPV-associated cervical cancer pinpointed CXCL17 in relation with Akt pathway and tumor progression." (PMID 38384293, 2024). "This is the first study, to the best of our knowledge, investigates the correlation between CXCL17 expression and cervical cancer tissues." (PMID 41496085, 2026). "Our findings revealed that CXCL17 promotes advancement of cervical cancer via influence of some critical EMT markers." (PMID 41496085, 2026). "In all 80 cervical cancer cases, CXCL17 expression was scored positively in 54 cases (67.50%), and 38 of them showed strong immunoreactivity." (PMID 41496085, 2026). "To elucidate the correlation between CXCL17 expression and EMT in cervical cancer, we performed immunostaining patterns of CXCL17 and relevant EMT markers, including E-cadherin, vimentin, and snail." (PMID 41496085, 2026). "The present study analyzed the CXCL17 expression pattern in cervical cancer and investigated its correlation with clinicopathological parameters in 80 cervical cancer cases." (PMID 41496085, 2026). "Correlation between CXCL17 and clinicopathological parameters in cervical cancer patients." (PMID 41496085, 2026). "Nevertheless, it is still unclear whether CXCL17 is correlated with tumorigenesis and advancement of cervical cancer." (PMID 41496085, 2026). "Taking into account the role of CXCL17 in lymph node metastasis and higher clinical stage, CXCL17 might be contribute to progression and metastasis of cervical cancer by EMT." (PMID 41496085, 2026). "Our experiments showed that CXCL17 expression was significantly correlated with lymph node metastasis and clinical stage, highlighting the vital role of CXCL17 in invasion and metastasis of cervical cancer." (PMID 41496085, 2026). "In 38 cervical cancer samples with lymph node metastasis, 30 samples showed CXCL17 immunoreactivity, indicating CXCL17 might involve in metastasis of cervical cancer." (PMID 41496085, 2026). "CXCL17 may contribute to invasion and metastasis of cervical cancer via EMT." (PMID 41496085, 2026). "Notably, CXCL17 immunoreactivity was detected in the cytoplasm of cervical cancer cells." (PMID 41496085, 2026). "In the present study, on the basis of a discovery cohort of 80 cervical cancer specimens, we explored the expression pattern of CXCL17 and GPR35 in cervical cancer cases." (PMID 41496085, 2026). "Then, we also examined CXCL17 protein expression and EMT-related markers in cervical cancer samples by immunohistochemical staining." (PMID 41496085, 2026). "By studying the correlations between CXCL17 and some EMT markers, we also investigated the role of CXCL17 in EMT of cervical cancer." (PMID 41496085, 2026). "Correlation of CXCL17 expression and EMT markers in cervical cancer tissues." (PMID 41496085, 2026). "Firstly, we investigated the expression pattern of CXCL17 in 80 paraffinembedded cervical cancer tissues and 25 noncancerous cervical epithelial tissues by immunohistochemistry." (PMID 41496085, 2026). "Our results indicate that CXCL17/GPR35 axis maybe participate in occurrence and development of cervical cancer." (PMID 41496085, 2026). "In conclusion, CXCL17 expression could be a latent marker of tumor progression and EMT in cervical cancer." (PMID 41496085, 2026).
cervical cancer (continued). "As a receptor for CXCL17, we also detected the GPR35 expression pattern in cervical cancer tissues." (PMID 41496085, 2026). "Hence, there was a significant difference of CXCL17 expression between cervical cancer tissues and noncancerous cervical epithelial tissues." (PMID 41496085, 2026). "Moreover, CXCL17/GPR35 axis maybe participate in occurrence and development of cervical cancer." (PMID 41496085, 2026).
coronary artery disease (3 papers, 2014 to 2019). "We aim to investigate the serum CXCL17 levels in different stages of patients with coronary heart disease and explore whether these differences contribute to atherosclerosis." (PMID 31934638, 2019). "Furthermore, the receptor for CXCL17, GPR35, has been implicated in pathogenesis of hypertension, coronary artery diseases, and cardiac hypertrophy." (PMID 29925869, 2018). "Other genes in this region include CIC, which is a transcriptional suppressor involved in early organ development, CNFN (involved in hematopoiesis), CXCL17 (involved in angiogenesis), and PAFAH1B3 (related to coronary artery disease and organ development)." (PMID 24555826, 2014).
idiopathic pulmonary fibrosis (3 papers, 2018 to 2023). Idiopathic pulmonary fibrosis (IPF) is a nonneoplastic pulmonary disease that is characterized by the formation of scar tissue within the lungs in the absence of any known cause. "Previous studies have shown that CXCL17 is strongly upregulated in idiopathic pulmonary fibrosis." (PMID 33717172, 2021). "Notably, CXCL17 was undetectable in the bronchioalveolar lavage of healthy subjects but expressed at significant levels in the bronchioalveolar lavage of patients suffering from idiopathic pulmonary fibrosis (IPF)." (PMID 29875152, 2018).
intraductal papillary mucinous neoplasm (3 papers, 2014 to 2025). "In premalignant intraductal papillary mucinous neoplasm, CXCL17 induced DC accumulation at the tumor site, which promoted tumor cell susceptibility to cytotoxic T cell-mediated cytolysis." (PMID 38654067, 2024). "CXCL17 is upregulated in premalignant intraductal papillary mucinous neoplasm, suggesting that it acts as a danger signal during the early stages of pancreatic carcinogenesis." (PMID 25303284, 2014). "In premalignant intraductal papillary mucinous neoplasm, CXCL17 induces DC accumulation at the tumor site, which promotes tumor cell susceptibility to cytotoxic T cell-mediated cytolysis." (PMID 25303284, 2014).
Achalasia (2 papers, 2016 to 2024). A disorder of esophageal motility characterized by the inability of the lower esophageal sphincter to relax during swallowing and by inadequate or lacking peristalsis in the lower half of the body of the esophagus. "Genes implicated in innate defense against pathogens, like CXCL17, IGHA1, and IGHA2, were down-regulated in patients with achalasia." (PMID 27511445, 2016). "Interestingly, among the most down-regulated genes, the chemokine (C-X-C motif) ligand 17 (CXCL17) and the immunoglobulin heavy constant alpha 1 and 2 (IGHA1-2) genes, play an important role in the innate defense against infections, supporting the hypothesis of process in triggering achalasia." (PMID 39337632, 2024).
lymphoma (2 papers, 2022 to 2024). A malignant (clonal) proliferation of B- lymphocytes or T- lymphocytes which involves the lymph nodes, bone marrow and/or extranodal sites. "The decreased expression of CCL28 and CXCL17, coupled with the increased expression of CCR1, may be linked to the progression of LGBLEL into lymphoma." (PMID 39451532, 2024). "Compared to the lymphoma group, the LGBLEL group showed higher expression of CCL28, CXCL17, HCK, GNB5, NRAS, and VAV2 (p = 0.012, 0.005, 0.009, 0.011, 0.008, and 0.003, respectively) and lower expression of CCR1 (p = 0.014)." (PMID 39451532, 2024). "WB revealed that, compared to the lymphoma group, the LGBLEL group exhibited significantly higher expression of CCL28, CXCL17, HCK, GNB5, NRAS, and VAV2 (p = 0.012, 0.005, 0.009, 0.011, 0.008, and 0.003, respectively) and lower expression of CCR1 (p = 0.014)." (PMID 39451532, 2024). "Compared to the lymphoma group, the protein quantitative analysis of the LGBLEL group exhibited significantly differentially expressed CCL28, CCR1, CXCL17, HCK, GNB5, NRAS, and VAV2 (p = 0.003, 0.011, 0.001, 0.024, 0.005, 0.019, and 0.031, respectively)." (PMID 39451532, 2024). "Compared to the lymphoma group, the LGBLEL group exhibited higher expression levels of CCL28, CXCL17, HCK, GNB5, NRAS, and VAV2 (p = 0.001, <0.001, <0.001, <0.001, 0.020, and <0.001, respectively) and lower expression of CCR1 (p = 0.002)." (PMID 39451532, 2024). "RT-qPCR showed that, compared to the lymphoma group, the LGBLEL group had significantly higher expression of CCL28, CXCL17, HCK, GNB5, NRAS, and VAV2 (p = 0.001, <0.001, <0.001, <0.001, =0.020, <0.001, respectively) and lower expression of CCR1 (p = 0.002)." (PMID 39451532, 2024). "The changes in the mRNA expression levels of CXCL1, CXCL3-8 and CXCL17 in lymphoma patients were not particularly significant (P > 0.05)." (PMID 35181719, 2022). "Similarly, CXCL17 was highly expressed in these regions in LGBLEL but not in the lymphoma group." (PMID 39451532, 2024).
ovarian carcinoma (2 papers, 2016 to 2021). A malignant neoplasm originating from the surface ovarian epithelium. "Our results showed that CXCL1, CXCL8, CXCL9, CXCL11, CXCL12, CXCL16, and CXCL17 were remarkably elevated in ovarian cancer compared to those in normal tissue." (PMID 33763130, 2021). "The human ovarian cancer cell lines (pre-spreading in vitro) showed dominant expression levels of CXCL1-3, 8 and CXCR4, while EOC (post-spreading in vivo) had higher levels of CCL20, CXCL17 and CXCR4." (PMID 27723802, 2016).
prostate carcinoma (2 papers, 2020 to 2023). A carcinoma that arises from epithelial cells of the prostate gland. "One study reported ventral prostate hyperplasia in estrogen receptor β−/− mice with a possible increased incidence of prostate cancer, while genetic analysis found a significant increase in CXCL17." (PMID 38075694, 2023). "Cochrane’s Q test did not provide evidence of heterogeneity between CCL18 (p = 0.767), CCL19 (p = 0.093), CCL24 (p = 0.935), CXCL17 (p = 0.210) and prostate cancer." (PMID 38075694, 2023). "Therefore, CXCL17 might also be a potential carcinogen of prostate cancer." (PMID 38075694, 2023).